IL18 (interleukin 18)
Diseases named in the same sentence as IL18 in open-access papers (continued):
Sharing a sentence is not in itself a finding about the gene and the disease.
kidney damage (continued). "It is reported that IL-18 levels rise around 6 h after kidney damage and peak between 12 and 18 h." (PMID 37761260, 2023). "Activation of TLR4 and the NLRP3 inflammasome promotes the maturation and release of caspase-1, along with downstream cytokines such as IL-1β and IL-18, triggering a persistent pro-inflammatory state crucial for the continued progression of hyperuricaemia nephropathy." (PMID 38041694, 2023). "IL-18 levels begin to rise roughly 6 h after kidney damage and peak between 12–18 h." (PMID 36091391, 2022). "In accordance with human reports, the present study and our previous studies showed that renal tubular inflammatory injuries were present in TCE-induced kidney damage, as evidenced by renal pathological examination and overexpression of IL-1β and IL-18 in renal tubules." (PMID 35656289, 2022). "These might include TGF-b1, CD80, podocalyxin, podocin, nephrin or uromodulin as nephropathy related biomarkers, and S1P or IL-18 as biomarkers more related to cardiomyopathy." (PMID 33924567, 2021). "Subjects with ESRD due to type 2 DM nephropathy differ in clinical manifestation from patients with other nephropathies leading to dialysis dependency, but differences in tested genotype distributions were found only in IL18 rs360719 compared with chronic tubulointerstitial nephritic patients." (PMID 25587543, 2014). "The elevated IL-1β and IL-18 levels are observed in diabetic patients with nephropathy." (PMID 22701621, 2012). "The predictive biomarkers approved by the FDA and EMEA for detecting kidney damage include the urine biomarkers of kidney injury molecule-1 (KIM-1), urinary neutrophil gelatinase-associated lipocalin (NGAL), interleukin-18 (IL-18), and liver fatty acid-binding protein (L-FABP)." (PMID 38002263, 2023). "In the current study, expression of Itgam, Nov, and Stab 2 increased and Ppard decreased in Il18−/− mice, suggesting that increased levels of Itgam and Nov and decreased expression of Ppard led to kidney damage in youth-aged mice, although high levels of Stab 2 might show some protective effects." (PMID 29514661, 2018). "CaOx can induce kidney damage and stone deposition by triggering the formation of GSDMD-N mediated membrane pores and the release of IL-18 and IL-1β via activation of the NLRP3 inflammasome." (PMID 40384863, 2025). "Another goal was to analyze the potential value of serum KIM-1, IL-18, and NGAL concentrations as predictors of kidney damage in children after alloHSCT with the use of artificial intelligence tools." (PMID 37958774, 2023). "The mRNA expression levels of early markers of kidney damage (KIM-1, IL-18, NGAL) in the renal tissue of the crush syndrome model were significantly suppressed in the TPEN-treated group." (PMID 36114355, 2022). "In this study, we demonstrated that treatment with an ADORA3 antagonist provides a renoprotective effect during the early stages of kidney damage in STZ-induced diabetic rats by decreasing the proinflammatory cytokines IL-1β and IL18." (PMID 31540220, 2019). "Some of these biomarkers that reflect kidney damage include kidney injury molecule-1 (KIM-1), NGAL, and interleukin-18." (PMID 28828020, 2017). "Several tubular injury markers have been reported as AKI biomarkers, including KIM-1, L-FABP, IL-18, NAG, and NGAL, which could indicate kidney damage prior to the increase in s-Cr." (PMID 37761260, 2023). "The biomarkers that reflect kidney damage (e.g., KIM-1, NGAL, and interleukin-18) can be utilized for the early detection of kidney damage even without functional damage." (PMID 28828020, 2017). "The levels of IL-11 do not increase.Inhibition of IL-18 cannot significantly prevent kidney damage.CCL5 and IL-1α significantly increase.Inhibition of TNF-α can significantly reduce kidney damage.NLRP3 pathway is less important." (PMID 34149721, 2021).
kidney damage (continued). "We also found that IL-18 but not NGAL and other indicators experienced a rising trend, suggesting that the postoperative kidney damage may be due to the ischemic effect of spinal anesthesia." (PMID 28222674, 2017).
endothelial dysfunction (43 papers, 2009 to 2026). In vascular diseases, endothelial dysfunction is a systemic pathological state of the endothelium (the inner lining of blood vessels) and can be broadly defined as an imbalance between vasodilating and vasoconstricting substances produced by (or acting on) the endothelium. "IL-18 is a cytokine associated with endothelial dysfunction." (PMID 34240250, 2022). "IL-18 is a pro-inflammatory cytokine that is predominantly produced by macrophages and binds to its receptor on the membranes of endothelial cells, lymphocytes, and smooth muscle cells to cause the production of interferon gamma, endothelial dysfunction, and plaque instability." (PMID 35997998, 2023). "IL-18 remains elevated for months post-infection and correlates with cardiovascular complications, including endothelial dysfunction and thromboinflammation." (PMID 40943354, 2025). "During ROS-induced endothelial dysfunction, ECs upregulate the expression of pro-inflammatory cytokines, including interleukin-1β (IL-1β) and interleukin-18 (IL-18)." (PMID 39974735, 2025). "Its mechanism of action involves preventing the oligomerization of the inflammasome complex, leading to decreased expression of inflammatory cytokines (such as IL-1β and IL-18), as well as reduced renal fibrosis, endothelial dysfunction, and oxidative stress." (PMID 40867825, 2025). "Compared to healthy controls, patients with axSpA and IBD had signs of endothelial dysfunction assessed by increased IL-18, ADMA levels and decreased fetuin-A level." (PMID 34240250, 2022). "Previous vascular functional studies confirmed that NLRP3 inflammasome plays a pivotal role in the regulation of endothelial dysfunction by activation of caspase-1, IL-1β, and IL-18 in metabolic disease models." (PMID 34326395, 2021). "Canonical NALP3 inflammasome activation is a caspase-1 medicated process, resulting in the secretion of IL-18 and IL-1β which lead to endothelial dysfunction." (PMID 30186184, 2018). "This activation leads to the rapid release of cytokines such as tumor necrosis factor-alpha (TNF-α), interleukin-1 beta (IL-1β), interleukin-6 (IL-6), and interleukin-18 (IL-18), driving systemic inflammation and leading to endothelial dysfunction, tissue damage, and increased vascular permeability." (PMID 39594987, 2024). "In recent years, several studies have shown that women with PCOS present with chronic low-grade inflammation, indicating abnormal expression of the proinflammatory cytokines interleukin-1 (IL-1), CRP, and interleukin-18 (IL-18), as well as endothelial dysfunction and increased oxidative stress." (PMID 37537636, 2023). "While CTCAs can detect epicardial atherosclerotic plaque with excellent sensitivity, microvascular disease cannot be identified on CT and may have an impact on serum levels of TRAIL, IL-18, and OPG, particularly considering their known associations with metabolic and endothelial dysfunction." (PMID 39334884, 2024). "The studies reviewed highlight a multifactorial process involving inflammatory agents such as CRP, S100 proteins, IL-18, IL-33, TNF, and osteopontin, alongside impaired HDL function, endothelial dysfunction, and altered immune cell profiles." (PMID 40943152, 2025). "PA also triggered inflammation and endothelial dysfunction, as evidenced by NLRP3 activation, upregulation of ICAM-1 (endothelial activation marker), and pyroptotic markers (NLRP3, GSDM-D, IL-1β, IL-18)." (PMID 39770410, 2024). "Our study demonstrated that PA-induced endothelial dysfunction significantly increased expressions of NLRP3, ICAM-1, GSDM-D, and pro-inflammatory cytokines IL-1β and IL-18 in the HUVECs during PA-induced pyroptosis." (PMID 39770410, 2024). "The results of this study indicate that Sil can decrease the expression of IL-18, NLRP3, caspase-1, and GSDMD and increase the expression of eNOS to inhibit inflammatory reaction and improve endothelial dysfunction." (PMID 37636019, 2023).
endothelial dysfunction (continued). "Studies have shown that inflammatory factors IL-6, IL-1β, IL-18, and TNF-α are positively correlated with cardiovascular events and are also involved in the occurrence of endothelial dysfunction." (PMID 33014270, 2020). "In order to delineate the pathogenesis of MDS-related endothelial dysfunction suggested by the prognostic impact of EASIX, we measured serum levels of S100A9, IL1β and IL18 (both activated by caspase 1 from pro-cytokines)." (PMID 31712595, 2019). "Similarly, IL-18 promotes Th1-driven inflammation by inducing IFN-γ production, aggravating oxidative stress, endothelial dysfunction, and myocardial injury." (PMID 40242450, 2025). "Low-grade systemic inflammation associated with PCOS is indicated by the high levels of inflammatory markers such as interleukin-18 (IL-18), C-reactive protein (CRP), white blood count, and monocyte chemoattractant protein-1 (MCP-1), along with increased oxidative stress and endothelial dysfunction." (PMID 33679617, 2021). "Moreover, in patients with axSpA and IBD, levels of serum markers of endothelial dysfunction differed from those in controls; specifically, compared to controls, patients with axSpA and IBD had increased serum IL-18 and ADMA levels and decreased serum fetuin-A level." (PMID 34240250, 2022). "Many cytokines such as TNF-alpha, IL-1, IL-2, IL-4, IL-6, IL-18, monocyte chemoattractant protein-1 (MCP-1), vimentin, and platelet-derived growth factor (PDGF) are produced by macrophages and T lymphocytes activated due to endothelial dysfunction and oxidative stress." (PMID 34349888, 2021). "A recent study reported that IL-18, which is induced by microglial TAK1 activation in the obese mouse brainstem, could act with the IL-18 receptor on endothelial cells to decrease the activity of eNOS, thereby resulting in endothelial dysfunction." (PMID 34461942, 2021).
diabetic nephropathy (42 papers, 2011 to 2025). "Activation of NALP3 inflammasome and secretion of IL-1β and IL-18 causes the development of tubulointerstitial disease in diabetic nephropathy." (PMID 30876398, 2019). "The current study aimed to evaluate the association of serum IL-18 and its promoter gene polymorphisms with diabetic nephropathy." (PMID 27703550, 2016). "Additionally, increased plasma and urinary levels of IL-18 are associated with early stages of diabetic nephropathy, as shown by its correlations with high-to-normal levels of albuminuria." (PMID 37372951, 2023). "In clinical studies, elevated plasma and urinary IL-18 levels were associated with diabetic nephropathy, and IL-18 was observed to be a predictive marker for the development of diabetic nephropathy in diabetic patients and to be associated with the progression of renal dysfunction." (PMID 33732720, 2021). "Elevated serum and urinary IL-18 levels in diabetic patients may be a risk factor for the development of diabetic nephropathy." (PMID 33732720, 2021). "Furthermore, a recent paper identified P-selectin and VCAM-1, as well as interleukin 18, as markers pathogenetically linked to, and predictive of diabetic nephropathy." (PMID 31906326, 2020). "This study aimed to determine the association of serum IL-18 level and its gene promoter polymorphism -607(C/A), -137(G/C) and -656(G/T) with diabetic nephropathy in the Saudi Arabia population as a step towards finding a reliable biomarker for diagnosis the DN disease." (PMID 27703550, 2016). "Inflammatory factors, particularly IL-18, strongly correlate with the progression of diabetic nephropathy." (PMID 40698245, 2025). "It was reported in the literature that the increase in IL-18 levels was parallel with the increase in IL-6 levels, in diabetic nephropathy." (PMID 37736511, 2023). "MALAT1 overexpression catalyzed pyroptosis in diabetic nephropathy to accelerate kidney impairment with the involvement of increased IL‐1β, IL‐18, Caspase-1, and GSDMD." (PMID 36243708, 2022). "In streptozotocin-induced diabetic nephropathy rats, chronic pioglitazone treatment reduced renal NFκB, IL-1β and IL-18 levels, depressed the glomerular mesangial expansion, and decreased serum BUN/creatinine." (PMID 34831270, 2021). "IL-1β and IL-18 appear to contribute to the progression of renal damage during diabetic nephropathy." (PMID 31540220, 2019). "Down-regulation of IL-18 expression can protect renal function and prevent the development of diabetic nephropathy." (PMID 29514661, 2018). "Inhibition of IL-18 protects renal function, such as prevention of the development of diabetic nephropathy." (PMID 29514661, 2018). "For instance, NF‐κB phosphorylation in renal tissues of mice with diabetic nephropathy and high glucose‐treated renal tubular epithelial cells promoted the release of IL‐1β and IL‐18, activating macrophages in the renal mesenchyme and aggravating tubular injury." (PMID 40391402, 2025). "IL18 is reported to be overexpressed in renal tissues in diabetic nephropathy." (PMID 35843953, 2022). "IL-18, produced by the inflammasome, correlates with the degree of urinary albumin excretion and is overexpressed in the tubular epithelial areas in renal tissues during diabetic nephropathy." (PMID 34830289, 2021). "Treatment that blocks IL-18 signaling may be a new approach in the treatment of diabetic nephropathy." (PMID 33732720, 2021). "In kidney tissue of diabetic nephropathy patients, IL-18 is overexpressed in tubular epithelial cells, which may occur via the activation of the MAPK pathways induced by transforming growth factor-beta (TGF-β)." (PMID 33732720, 2021).
diabetic nephropathy (continued). "In addition, a Japanese study reported that serum IL-18 was correlated with carotid intima-media thickness and urinary albumin excretion in diabetic nephropathy patients." (PMID 32487168, 2020). "NLRP3, IL-1β, and IL-18 in rats with diabetic nephropathy were markedly increased." (PMID 30555415, 2018). "Interestingly, similar to IL-6, IL-18 has also been reported to be enhanced in serum and urine samples of patients with diabetic nephropathy compared to controlled subjects, and higher IL-18 levels in turn increase UAE as evidenced by many clinical studies." (PMID 28164134, 2017). "Thus, IL-18 might be an important factor not only in the atherosclerosis processing but also, in the development and progression of diabetic nephropathy." (PMID 27703550, 2016). "Inflammatory factors such as interleukins (IL-1, IL-6, IL-18) and tumor necrosis factor (TNF-α) are activated in diabetic nephropathy, promoting kidney damage through various signaling pathways." (PMID 40698245, 2025). "Interleukin 1 (IL-1), IL-6, IL-18, and tumor necrosis factor (TNF) are considered the crucial inflammatory cytokines in diabetic nephropathy." (PMID 35295847, 2022). "These include IL-1, IL-6, IL-18, and TNF-α which are mainly involved in the development and progression of diabetic nephropathy." (PMID 28164134, 2017). "Inflammatory cytokines such as IL-1β, IL-18, TNF-α, MCP-1, and ICAM-1 are significantly increased in renal tissues during diabetic nephropathy and attenuating the expression of these cytokines may protect against diabetic renal injury." (PMID 26881256, 2016). "Serum IL-18 levels were elevated in patients with diabetic nephropathy, but not in other diabetic complications." (PMID 26273672, 2015).
heart failure (42 papers, 2008 to 2026). Inability of the heart to pump blood at an adequate rate to meet tissue metabolic requirements. "Several pro-inflammatory cytokines, including tumor necrosis factor-alpha (TNF-alpha), interferon-gamma, interleukin-1-beta, interleukin-6, interleukin-17, and interleukin-18 have been implicated in the pathogenesis of heart failure." (PMID 33391898, 2021). "A study of follow-up (of mean 2.4 years) underlighted that subjects who died for heart failure had higher serum values of IL-18 compared with those still alive." (PMID 28174512, 2017). "The risk prediction of circulating IL-18 levels has previously been demonstrated regarding CV mortality, heart failure, MI and deaths in patients diagnosed with ACS, and in healthy men suffering coronary events." (PMID 24040261, 2013). "Compared with heart failure-associated transudative ascites, malignant ascites demonstrated higher levels of TNF-α, IL-6, IL-10, IL-12p70, IL-18, IL-23, s4-1BB, and TGF-β1, while albumin levels were lower." (PMID 42193466, 2026). "Since 1990, studies have confirmed elevated levels of various inflammatory mediators, including TNF-α, IL-6, IL-1β, IL-18, and immune antigens, in the plasma of heart failure patients." (PMID 40671145, 2025). "In the pathophysiology of heart failure, previous data demonstrated the critical roles of active IL-1β and IL-18." (PMID 38750444, 2024). "The inflammasome exerts an inflammatory effect by regulating the release of proinflammatory cytokines including IL-1β and IL-18, contributing to cardiomyocyte apoptosis and dysfunction, and leading to ventricular remodeling and heart failure." (PMID 36704451, 2022). "In patients with heart failure, interleukin-18 (IL-18) levels increase in the circulatory system and injured myocardial tissue." (PMID 37551283, 2022). "IL18 levels have indeed been associated with increased mortality and are inversely correlated with LVEF in heart failure." (PMID 33193300, 2020). "As revealed in previous clinical studies, the levels of IL-6 and IL-18 are increased in patients affected by heart failure." (PMID 31384408, 2019). "High levels of IL-18 in the serum increased cardiovascular disease mortality, such as heart failure and AMI/R." (PMID 31011288, 2019). "A recent study showed that IL-18 is a predictor of mortality for heart failure in a group of octogenarians." (PMID 28174512, 2017). "Patients with heart failure have also been reported to show increased IL-18 but decreased IL-18BP levels." (PMID 22761702, 2012). "IL-18 is an established biomarker of heart failure, so that it has been proposed that anti-IL-18 treatment may have therapeutic effects in patients with SCD at risk for cardiac arrhythmias and adverse outcomes." (PMID 36969226, 2023). "Interestingly, increased circulating levels of IL‐18 have been found in patients with decreased skeletal muscle mass, including sarcopenia, heart failure, and chronic obstructive pulmonary disease (COPD)." (PMID 35146955, 2022). "It is also worth noting that the caspase-1 downstream inflammatory cytokines, IL-1β and IL-18, accelerate the transition from cardiac remodeling to heart failure and thus are expected to be potential drug targets for heart failure." (PMID 33842546, 2021). "Considering the dilated cardiomyopathy (DCM) as a relatively high-incident disease leading to heart failure, the aim of this study is to determine the difference in the expression level of interleukin (IL)-6 and IL-18 in patients with ischemic and idiopathic DCM." (PMID 31384408, 2019). "In addition, IL-18 levels in both the circulation and resident myocardial tissues are increased in patients with heart failure." (PMID 27888626, 2016). "Because of the deteriorated role of IL-18 in cardiovascular disorders, blockage of the IL-18-induced inflammatory responses has been considered the potential therapeutic strategy for vascular dysfunction and heart failure, e.g. LPS-induced myocardial dysfunction." (PMID 27888626, 2016).